CPT1C (carnitine palmitoyltransferase 1C)
Diseases named in the same sentence as CPT1C in open-access papers (continued):
Sharing a sentence is not in itself a finding about the gene and the disease.
neuroblastoma (2 papers, 2020). Neuroblastoma (NB) is the most common solid, extracranial childhood tumor. "MYCN-amplified neuroblastoma cells show high levels of CPT1C expression, and inhibition of both CPT1C and peroxisomal β-oxidation leads to lipid accumulation." (PMID 32547946, 2020). "High expression levels of CPT1C, a brain-specific metabolic enzyme, in N-Myc-positive neuroblastoma cells suggest that increased FAO might be an important metabolic feature in this malignancy." (PMID 32547946, 2020). "Accordingly, the FAO inhibitor etomoxir, which inhibits the rate-limiting FAO enzyme carnitine palmitoyltransferase 1 (CPT1C), suppresses the growth of xenograft tumors derived from MYCN-amplified neuroblastoma." (PMID 32547946, 2020).
amyloidosis (1 paper, 2021). A disorder characterized by the localized or diffuse accumulation of amyloid protein in various anatomic sites. "Studies have noted that PPARα regulates the malignant behaviors of tumor cells by targeting CPT1C, and PPARα activation can alleviate the amyloidosis and reverse memory deficits and anxiety in AD." (PMID 34424821, 2021).
bladder cancer (1 paper, 2023). "However, not all tumor types benefit from CPT1C expression, since human bladder cancer samples compared to normal adjacent tissues show decreased levels of CPT1C." (PMID 36693836, 2023).
chronic myelogenous leukemia (1 paper, 2019). "In chronic myelogenous leukemia that are addicted to glucose metabolism for survival, inhibition of mTORC1 by rapamycin or S6K1 knockdown led to increased fatty acid oxidation and increased the expression of the fatty acid transporter carnitine palmitoyl transferase 1c (Cpt1c)." (PMID 31817676, 2019).
Cognitive impairment (1 paper, 2025). Abnormal cognition is characterized by deficits in thinking, reasoning, or remembering. "Notably, both patients also presented with a range of neurological symptoms beyond those typically associated with CPT1C variants, including cognitive impairment, seizures, neurobehavioral disorders, and psychiatric symptoms." (PMID 39737739, 2025).
epilepsy (1 paper, 2024). A brain disorder characterized by episodes of abnormally increased neuronal discharge resulting in transient episodes of sensory or motor neurological dysfunction, or psychic dysfunction. "Four diagnostic biomarkers (ALOX12B, CBS, CPT1C, and DAGLB) showed high accuracy for epilepsy diagnosis, with an AUC value of 0.9592." (PMID 38419709, 2024). "Our research unveiled potential DELMRGs (ALOX12B, CBS, CPT1C and DAGLB) in TSE, which may provide new ideas for studying the psathogenesis of epilepsy." (PMID 38419709, 2024). "Our research identified potential DELMRGs (ALOX12B, CBS, CPT1C, and DAGLB) in epilepsy, which may provide new ideas for studying the pathogenesis of Epilepsy." (PMID 38419709, 2024).
esophageal squamous cell carcinoma (1 paper, 2024). Esophageal squamous cell carcinoma (ESCC) is a type of esophageal carcinoma (EC) that can affect any part of the esophagus, but is usually located in the upper or middle third. "Clinically, high CPT1C expression correlated with poor survival in patients with esophageal squamous cell carcinoma." (PMID 38783346, 2024). "Clinically, esophageal squamous cell carcinoma (ESCC) patients with high expression levels of CPT1C represented significantly poor prognosis." (PMID 38783346, 2024). "Therefore, CPT1C could be an independent prognostic indicator in esophageal squamous cell carcinoma." (PMID 38783346, 2024).
non-small cell lung carcinoma (1 paper, 2023). A group of at least three distinct histological types of lung cancer, including non-small cell squamous cell carcinoma, adenocarcinoma, and large cell carcinoma.
cancer (64 papers, 2012 to 2025). A tumor composed of atypical neoplastic, often pleomorphic cells that invade other tissues. "CPT1C, functioning as a rate-limiting enzyme in fatty acid oxidation, exhibits a close association with cancer cell viability, tumor progression, resistance to therapeutic agents, and cellular senescence." (PMID 38012244, 2023). "PTC tissues are associated with a high level of Cpt1c expression, and Cpt1c up-regulation promotes cancer cell growth and metastasis." (PMID 35008887, 2021). "A previous study has revealed a vital role of CPT1C in cancer cell proliferation, metabolism and senescence-associated mitochondrial dysfunction." (PMID 32641987, 2020). "Our previous study confirmed that low CPT1C expression plays a crucial role in RS and further identified CPT1C as a novel biomarker and key regulator of cancer cell senescence through mitochondria-associated metabolic reprogramming." (PMID 32289751, 2020). "CPT1C is regulated by AMPK causing tumor growth during metabolic stress in various cancer cell types, and CPT1C down-regulation enhanced sensitivity to rapamycin in cancer cells." (PMID 32133293, 2020). "Further studies have shown that CPT1C is not only associated with cellular senescence but also closely linked to the regulation of cancer cell lipotoxicity and tumor immunity, which contributes to a deeper understanding of the importance of CPT1C as a therapeutic target." (PMID 39596847, 2024). "Additionally, a study using The Cancer Genome Atlas (TCGA) dataset showed that CPT1C is part of the 5-gene metabolic signature associated with epithelial-mesenchymal transition, metastatic progression, and poor prognosis across multiple cancers." (PMID 36693836, 2023). "Studies have shown that CPT1C is highly expressed in cancer cells, and it favors tumor survival by helping cancer cells adapt to nutrient depletion and hypoxia via enhancing the oxidation of fatty acids and the production of ATP." (PMID 39859448, 2025). "Upregulation of CPT1c has been seen in many cancers, likely as a mechanism to generate ATP and NADPH in response to glucose deprivation." (PMID 39883710, 2025). "There have been studies reporting that the expression of CPT1C is correlated with the senescence phenotype of cancer cells, which also provides a new research angle for the phenotypic study of other CPTs." (PMID 39596847, 2024). "The assumption that CPT1C is located in the mitochondrial external membrane of cancer cells is still a controversial assumption." (PMID 36693836, 2023). "The roles of CPT1C in cancer have scarcely been investigated, and few studies have attempted to investigate the prognostic value of CPT1C in CRC." (PMID 37078750, 2023). "In cancer cells, CPT1C expression is known to regulate lipid metabolic reprograming and cell adaptation to environmental stressors." (PMID 37760915, 2023). "In fact, CPT1C silencing has been proposed as a potential cancer-treatment strategy to induce senescence and halt tumour proliferation." (PMID 36674468, 2023). "The potential use of CPT1C inhibitors for cancer treatment would apply only to HER2- and hormone positive BC patients." (PMID 36674468, 2023). "In the cancer field it is assumed that the function of CPT1C—like that of the other canonical CPT1 proteins—is to facilitate FA transport to the mitochondrial matrix to boost FAO." (PMID 36693836, 2023). "We also review the clinical relevance of CPT1C as a prognostic indicator and its contribution to tumor growth, cancer invasiveness, and cell senescence." (PMID 36693836, 2023).
cancer (continued). "Tumor tissue samples from patients with various cancers, especially breast cancer and pancreatic cancer, show higher CPT1C expression compared with normal tissue 15, 17-21." (PMID 37151873, 2023). "Targeting these miRNAs has been proposed as a therapeutic strategy to combat malignant cancers with high CPT1C expression." (PMID 36693836, 2023). "Numerous reports demonstrate the key role of CPT1C in human-derived cancer cell lines in response to metabolic stress." (PMID 36693836, 2023). "In summary, we are of the opinion that CPT1C in cancer cells behaves as a nutrient sensor that facilitates tumor progression and metabolic adaptation to environmental stressors through regulation of SAC1, protrudin, ABHD6, and possibly other proteins." (PMID 36693836, 2023). "In the past decade, an array of publications have demonstrated how CPT1C enables cancer cells to adapt their lipid metabolism to resist stressful conditions such as hypoxia and glucose deprivation, avoid cellular senescence, and enhance tumorigenesis." (PMID 36674468, 2023). "This new and integrated vision of CPT1C function can help better understand the metabolic plasticity of cancer cells and improve the design of therapeutic strategies." (PMID 36693836, 2023). "Several studies report that CPT1C is involved in cancer cell adaptation to nutrient depletion and hypoxia." (PMID 36693836, 2023). "This idea arises from the very first study linking CPT1C to cancer, which reported that CPT1C overexpression increases FAO in MCF7." (PMID 36693836, 2023). "On the other hand, glucose depletion or glycolysis inhibition by 2-deoxy-D-glucose also increase CPT1C mRNA levels in different cancer cell lines." (PMID 36693836, 2023). "Here, we exhaustively review the literature and question the role of CPT1C as a facilitator of FA entry in the mitochondria of cancer cells." (PMID 36693836, 2023). "Before rethinking the role of CPT1C in cancer cells, it is worthwhile reviewing its function in neurons." (PMID 36693836, 2023). "Overall, those data point to an important role for CPT1C in mitochondrial function and in lipid metabolism in cancer cells that goes beyond FAO modulation." (PMID 36693836, 2023). "All that evidence points to the idea that CPT1C is necessary to maintain normal mitochondrial performance in cancer cells." (PMID 36693836, 2023). "In order to clarify how miR-377-3p regulates CPT1C expression in cancer cells, we transfected wild-type or mutant CPT1C 3′-UTR luciferase reporter and miR-377-3p into HepG2 and MHCC97H cells." (PMID 35057851, 2022). "As the role of FAO in cancer progression has been increasingly recognized, we then focused on CPT1C to examine its significance in GC, especially in the distant metastasis to the ovary." (PMID 35593464, 2022). "CPT1C has been found by others to facilitate cancer progression by promoting proliferation, tumor growth, and survival, increasing ATP synthesis to protect against metabolic stress, contributing to chemoresistance, and preventing cancer cell senescence." (PMID 35936710, 2022). "Despite the fact that CPT1C is ubiquitously presented in various transformed cells and cancers, the current strategy we used for the following study is to detect its expression in vitro." (PMID 34424821, 2021). "OLD and 6 drugs downregulated GLS1 and HK2, two targets of the drugs schemes, as well as CPT1C, a regulator of fatty acids transport into mitochondria for β-oxidation and of cancer cell senescence through metabolic reprogramming." (PMID 33664364, 2021).
cancer (continued). "CPT1 (carnitine palmitoyltransferase) is responsible for FA import into the mitochondria, and the high expression of CPT1 isoform Cpt1c is induced to promote cancer cell survival in conditions of metabolic stress." (PMID 35008887, 2021). "Carnitine palmitoyltransferase 1C (CPT1C), an enzyme that has an important role in the beta-oxidation of long-chain fatty acids, has been shown to regulate cancer cell senescence through mitochondria-associated metabolic reprogramming." (PMID 33282950, 2020). "Another biomarker of cancer metabolism is CPT1C, a member of the CPT1 family that catalyzes fatty acid acylation and entry into mitochondria for β-oxidation." (PMID 32641987, 2020). "More importantly, knockdown of CPT1C in cancer cells induced mitochondrial dysfunction, senescence-like growth suppression and cellular senescence and further suppressed malignancy and tumorigenesis in vivo and xenograft tumor growth in situ." (PMID 32289751, 2020). "The knockdown of CPT1C inhibited the tumorigenesis of PANC-1 cells in vivo and further suppressed xenograft tumor growth in situ, suggesting that CPT1C represents a therapeutic target for cancer treatment." (PMID 32289751, 2020). "AMPK frequently induces CPT1C in aggressive cancers to promote cancer cell survival under metabolic stress." (PMID 30771209, 2019). "In cancer cells, CPT1C is induced by hypoxia and glucose deprivation, its expression inversely correlates with mTORc1 activation and it promotes cell survival by stimulating FA oxidation and ATP production." (PMID 30081476, 2018). "Since a truncated form of CPT1C has been demonstrated in the nuclei of human diffuse gliomas, new perspectives are opening on the role of CPT1C expression in cancer cells." (PMID 29445084, 2018). "Using gene expression profiles, we established a gene-signature (CAV1, CD36, MLXIPL, CPT1C, CYP2E1) that strongly associated with epithelial-mesenchymal program across multiple cancers." (PMID 26725848, 2016). "It is earlier reported that expression of CPT1C, a brain‐specific enzyme, in cancer cells promoted FA oxidation, ATP production, resistance to glucose deprivation, and tumor growth." (PMID 24646661, 2014). "It was reported that carnitine palmitoyltransferase 1C (CPT 1C) overexpression in cancer is important for cancer cell survival and resistance to therapy." (PMID 24040298, 2013). "Similarly, estrogen-related receptor α, miR-1291, and CPT1C collectively regulate cancer cell proliferation, energy metabolism, and oncogenic transformation." (PMID 41219902, 2025). "CPT1C is a well-known fatty acid oxidation gene frequently upregulated in cancer cells." (PMID 39859448, 2025). "Current evidence underscores that CPT1C plays a predominantly pro-cancer role in most cancers." (PMID 39596847, 2024). "Currently, the majority of studies have demonstrated that despite CPT1C exhibiting suboptimal catalytic activity and being situated within the endoplasmic reticulum, it still affects the malignant biological learning of cancer cells by altering downstream FAO rates." (PMID 39596847, 2024). "In thyroid-like carcinoma, AMPK activates and protects against hypoxia- and hypoglycemia-induced cancer cell death by influencing the level of CPT1C expression in response to stimuli such as external anthropogenic interventions lowering oxygen concentration or glucose levels." (PMID 39596847, 2024). "Targeting of CPT1C may offer an opportunity to modulate cancer cell metabolism and slow tumor growth." (PMID 37151873, 2023). "CPT1C has been described almost exclusively in neurons, stem cells, and cancer cells." (PMID 37760915, 2023). "CPT1C is expressed almost exclusively in neurons, stem cells, and cancer cells." (PMID 36693836, 2023).
cancer (continued). "Interestingly, CPT1C overexpression in senescent cells can reverse the phenotype, while CPT1C downregulation recapitulates senescence in diverse cancer cell lines, leading to lower proliferation, migration, and invasion rates, and reduced in vivo tumor growth." (PMID 36693836, 2023). "To date, the notion that CPT1C could promote malignant phenotype transition has been revealed in several other cancers." (PMID 37078750, 2023). "Furthermore, we compared the expression of CPT1C between 64 paired cancer and adjacent normal tissues from our cancer center and found that CPT1C is highly expressed in cancer tissues." (PMID 37078750, 2023). "However, in the cancer field, most authors assume that CPT1C has the same catalytic function as the other canonical members of its enzyme family, and that CPT1C is a specific marker of FAO." (PMID 36693836, 2023). "CPT1C has also been defined as a novel regulator of cancer cell senescence." (PMID 36674468, 2023). "CPT1C has been reported to take an active role in cancer development and progression." (PMID 35057851, 2022). "We suggested that CPT1C might play a critical role in regulating tumor cell motility, invasiveness, transformation, and maintenance of cancer stem cell properties in BLBC." (PMID 35936710, 2022). "These lines of evidence put forward potential strategies by which targeting the miR-377-3p/CPT1C axis may provide a therapeutic window for cancer treatment." (PMID 35057851, 2022). "Moreover, the ability of miR-377-3p inhibitor to promote the growth of cancer xenografts were abolished by CPT1C knockdown." (PMID 35057851, 2022). "Furthermore, we elucidated the role of CPT1C in GC progression through comprehensive analyses of cancer-OMICS databases, a similar strategy which was adopted in a previous study." (PMID 35593464, 2022). "Since Cpt1c can protect cancer cells from stress-mediated death and contribute to PTC development and progression, the application of Cpt1c inhibitors (alone and in combination with AMPK agonists) could be used as a new promising way in PTC treatment." (PMID 35008887, 2021). "CPT1-C is a brain- and cancer-specific isoform with an unclear role in FAO." (PMID 33291682, 2020). "Indeed, CPT1-C is the cancer- and brain-specific isoform of mitochondrial CPT1 that is inhibited by malonyl-CoA." (PMID 33291682, 2020). "Since both miR-1291 and CPT1C regulate tumor cell metabolism and cancer progression, we hypothesized that they might be regulated synergistically." (PMID 32641987, 2020). "In addition to CPT1A, AMPK regulates CPT1C expression to promote tumor growth upon metabolic stress in several types of cancer cells." (PMID 29996946, 2018). "Down-regulation of CPT1C enhances the sensitivity to mTOR inhibitor, rapamycin in cancer cells." (PMID 29996946, 2018). "It is thus possible that CPT1C activates autophagy and lipid droplet biogenesis to promote cancer cell survival through lipid droplet lipolysis, which, in turn, provides FAs for oxidation in mitochondria and stimulation of PPARα-mediated mitochondrial biogenesis and oxidative metabolism." (PMID 30081476, 2018). "Therefore, it is suggested that CPT1C promotes cancer cell survival and tumor growth and it has been proposed as a new therapeutic target in cancer treatment." (PMID 25698923, 2014). "A recent study on the role of CPT1c in cancer cells in response to metabolic stress showed that CPT1c could participate in protecting cells from stress." (PMID 23098614, 2012). "In cancer, CPT1C may act as a metabolic sensor or modulator of cellular senescence." (PMID 41219902, 2025).